MMP9 (matrix metallopeptidase 9)
Diseases named in the same sentence as MMP9 in open-access papers (continued):
Sharing a sentence is not in itself a finding about the gene and the disease.
tumor (continued). "In our study, we found several MMP molecules to be significantly overexpressed in metastatic cell lines compared to primary tumor cells (e.g., MMP1, MMP2, MMP3, MMP9), with a dramatic increase registered for MMP2." (PMID 37047539, 2023). "MMP2 and MMP9 are gelatinases of the MMP family, which degrade extracellular matrix and are involved in tumour invasion, metastasis and immune surveillance." (PMID 36457281, 2023). "Matrix metalloproteinases MMP1, MMP2, MMP3 and MMP9, which are involved in extracellular matrix (ECM) remodeling and promotion of tumor cell migration and invasion, were also significantly increased (p < 0.0001) in metastatic cell lines compared to PM cells." (PMID 37047539, 2023). "Under serum deprivation, FOXO3a supports the induction of MMP9 and MMP13 and thus increases tumor invasiveness." (PMID 38136293, 2023). "These ingredients can potentially decrease the levels of inflammatory cytokines (such as IL-6 and TNF-α), inhibit the expression of tumor-related factors (such as JAK2/STAT3, MMP-9, and vimentin), and increase immune cell activity." (PMID 37742025, 2023). "The analysis showed that the content of HSP60+, MMP9+MMP2+TIMP-, MMP9+2-TIMP-, and MMP9+2-TIMP+ populations of sEVs differed in patients with complete and partial tumor response." (PMID 37109070, 2023). "Notably, MMP-9 concentrations in circulating blood were elevated approximately 50-fold (range 3–5 ng/ml to 200–300 ng/ml) during metastasis, which may contribute to angiogenesis and the spread of tumor cells to distant organs." (PMID 37185776, 2023). "Taken together, these data showed that mouse cardiac-specific expression of Cre recombinase leads to development of tumor-like lesions in the atrium, along with strong significant upregulation of MMP-2 and MMP-9 after six months of age." (PMID 36834504, 2023). "MMP-9 and CCR7 positivity in tumor cells were seen in the cytoplasm and appeared as brown particles." (PMID 37600570, 2023). "EGCG decreased AsPC-1 xenograft tumor volume, angiogenesis, and metastasis together with downregulation of MMP2, MMP7, MMP9, and MMP12." (PMID 36677584, 2023). "In this study, we analysed the effect of DFOM in ESCC tumour progression by targeting LCN2, and the LCN2/LOXL2/MMP9 complex as well." (PMID 37753805, 2023). "In this study, we found that diHEP-DPA significantly inhibited the infiltration of TAMs and decreased the secretion of MMP2, MMP9, VEGF, IL-6, and TNF-α in tumor tissue." (PMID 36827121, 2023). "In xenografted animal models of tumor and HeLa cells, CBS downregulated the expressions of nuclear-translocated p65 and molecules downstream of NF-κB (XIAP, Bcl-xL, MMP-2, MMP-9, COX-2, and cyclin D1) by inhibiting the NF-κB signaling pathway." (PMID 37063281, 2023). "BC002811 regulated three differentially expressed genes (MMP2, MMP9, and PTEN) out of 84 key genes involved in human tumor metastasis." (PMID 36778127, 2023). "M2 macrophages secrete various cytokines such as MMP-9, MMP-2, MMP-12,VEGFIL-8, IL-1 and fibroblast growth factor to induce tumour angiogenesis and a worsened prognosis." (PMID 37742025, 2023). "AS-IV upregulates the levels of Ki67, MMP-2, and MMP-9 by regulating the MAPK/ERK signaling pathway, which further results in the suppression of tumor cell growth, migration, and invasion abilities." (PMID 37063281, 2023). "In melanoma, miR-155 derived from the tumor inhibits SOCS1 and promotes the activation of the JAK2/STAT3 signaling pathway, increasing FGF2, VEGFA, and MMP9 levels in CAFs." (PMID 37605155, 2023). "Downregulation of FOXO6 promotes tumor invasion, because FOXO6 transcriptionally regulates Sirt6, which suppresses the secretion of MMP9." (PMID 38136293, 2023). "CXCL5 (epithelial neutrophil-activating peptide-78) and MMP-9 also recruit neutrophils in Hepato-Cellular Carcinoma (HCC) and promote tumor progression and metastasis." (PMID 37376417, 2023).
tumor (continued). "A positive correlation between MMP-9 (gelatinase B) and MMP-11 (stromelysin-3) proteins and increased tumor aggressiveness has been revealed." (PMID 36793738, 2023). "The upregulation of MMP-2, MMP-9 and Vimentin and the inhibition of E-cadherin in tumor cells will promote EMT and contribute to tumor invasion." (PMID 37367063, 2023). "Correlation analysis displayed that the metastatic rates of the tumor cells were positively correlated with the expression of ANKRD49, MMP-2, MMP-9, p-JNK, p-c-Jun or p-ATF2." (PMID 37964204, 2023). "The macrophages in the invasive zone exhibited an M2-like phenotype with increased expression of CD163, MRC1, and SAAs receptor TLR2, whereas macrophages in the tumor tissue exhibited features of ECM remodeling and increased expression of MMP9 and MMP14." (PMID 37337030, 2023). "The result of the statistical analysis did not confirm any correlation between the expression of the studied genes (MMP2, MMP9, TIMP1) in blood and tumor tissue." (PMID 37509417, 2023). "In tumor cells, LRP1, as the endocytic receptor of MMP2 and MMP9, can make malignant cells in an adherent state by activating ERK and inhibiting the JNK signaling pathway, which is conducive to invasion 49,50,51." (PMID 36605486, 2023). "Tumor EVs induce an upregulation of genes important for extracellular matrix remodeling (i.e., MMP2 and MMP9)." (PMID 38293652, 2023). "MMP9 can induce the expansion of myeloid derived suppressor cells (MDSC) and promote tumor immune escape." (PMID 36560848, 2023). "The knockdown of Radixin by shRNA in glioblastoma U251 cells was found to significantly inhibit tumor growth and upregulate thrombospondin-1 (TSP-1) and E-cadherin while downregulating MMP9." (PMID 37371090, 2023). "Further, major MMPs involved in promoting tumor angiogenesis, which is an important step for tumor vascularization and also represents an avenue for metastasis, include MMP-2, MMP-9 and MMP-14." (PMID 37091337, 2023). "These iMCs displayed CCR1 expression enabling migration along with CCL9 gradient, as well as intense production of matrix metalloproteinases MMP9 and MMP2; therefore, the iMCs promoted tumor invasion." (PMID 37185750, 2023). "PTEN expression not only affects cellular proliferation and growth, but the tumor suppressor also inhibits migration via suppressing effects on various MMPs, including MMP2 and MMP9." (PMID 37313172, 2023). "During tumor initiation, signaling induced by M1-polarized macrophages also upregulates expression of MMP3, MMP7, MMP9, MMP10 and MMP13 in acinar cells, and MMP9 has been demonstrated to drive the ADM process via microenvironment remodeling." (PMID 37638028, 2023). "Invasive pseudopodia can recruit the proteases MMP-9 and MMP-14 to the leading edge, where they degrade ECM and basement membrane, thereby promoting tumor invasion and metastasis." (PMID 37670313, 2023). "Altogether, these findings argue for an active role of TAM in promoting tumor angiogenesis through VEGF- and MMP-9-dependent pathways." (PMID 37234993, 2023). "TANs also accumulate in tumor tissues and secrete elastase, which promotes EMT and secretion of MMP-9 in pancreatic cancer, and promotes tumor invasion and angiogenesis." (PMID 37064113, 2023). "Following tumor penetration across the brain endothelial barrier, the tumor cells invaded the ECM, as indicated by several epithelial–mesenchymal transition markers, including endopeptidases, MMP-2 and MMP-9, and an invasion marker, TWIST." (PMID 38001146, 2023). "Mechanistically, SHH can induce epithelial–mesenchymal transition (EMT), matrix metalloproteinase 9 (MMP-9) activity and tumor lymphangiogenesis through the PI3K/Akt pathway, thereby promoting tumor progression and LN metastasis." (PMID 37803421, 2023). "MMP2 and MMP9 are overexpressed in many tumors, and high MMP2 and MMP9 levels promote tumor metastasis and progression." (PMID 37521428, 2023).
tumor (continued). "In clear cell renal carcinoma (CCRC), the overexpression of CLU regulates tumor progression and metastasis of human CRCC cells via modulation of ERK1/2 signaling and MMP-9 expression." (PMID 37685987, 2023). "Pro-tumor N2 neutrophils are known to influence cancer progression by the secretion of C-X-C motif chemokine ligand 1 (CXCL1), matrix metallopeptidase 9 (MMP-9), VEGF, and TNF-alpha, as well as ROS and NO." (PMID 37427115, 2023). "Two matrix metalloproteinases (MMPs) MMP2 and MMP9 are the endopeptidases involved in ECM remodeling, EMT, and tumor cell invasion." (PMID 37963859, 2023). "IL-17 and transformed colonic epithelial cells promote tumor development by inhibiting immune effector cells and activating the STAT3 signaling pathway, as well as the secretion of pro-angiogenic mediators, matrix metalloproteinase 9 (MMP9), and VEGF." (PMID 36950522, 2023). "Integrin αvβ3 is necessary for tumor cell adhesion to the extracellular matrix (ECM) by targeting RGD (Arg-Gly-Asp) in fibronectin and regulates MMP (especially MMP-2 and MMP-9) expression through the PI3K signaling pathway to hydrolyze collagen in the ECM." (PMID 37862114, 2023). "MMP2 and MMP9 are well-known tumor metastasis markers, while PTEN is a well-characterized tumor suppressor gene that plays a major role in the metastasis of GC 15-17." (PMID 36778127, 2023). "Perioperative continuous intravenous infusion of Lido and Dex significantly reduced the production of NETs (MPO and H3Cit) and the expression of tumor metastasis biomarkers (VEGF-α, MMP-3, and MMP-9) in the peripheral blood of NSCLC patients." (PMID 36910600, 2023). "The IHC staining revealed a significant decrease in the expression of MMP-2, MMP-9, N-cadherin, and Vimentin in DMC-HA-treated tumor tissues." (PMID 38154100, 2023). "MMPs exert important effects in tumor invasion and metastasis, among which MMP2, MMP3 and MMP9 are the main members that play crucial roles in the invasion and metastasis of cancer cells." (PMID 37100464, 2023). "These are well-known to promote tumor development through tissue remodeling; they secrete proteases, such as matrix metalloproteinase-2 (MMP-2) and matrix metalloproteinase-9 (MMP-9)." (PMID 36986856, 2023). "The inhibition of neutrophil extracellular traps by a paclitaxel prodrug nanoparticle core and poly-l-lysine conjugated with matrix metalloproteinase 9 (MMP-9) prevented the migration of neutrophils into the tumor microenvironment and into the tumor itself." (PMID 38139365, 2023). "Differentiated cells at days 26 and 30, characterized by negligible expression levels of TIMP1, MMP9 and CD44, were unable to induce tumor growth." (PMID 36906579, 2023). "An investigation explores the action of Nrf2 in GBM U251 cells and reveals the collaboration between Nrf2 and matrix metalloproteinase 9 (MMP9), which is a positive indicator for tumor cell migration and invasion." (PMID 37810967, 2023). "The expression levels of MMP9, VWF, VEGFA, SERPINE1, and TIMP1 in ccRCC tissues were higher than those in normal tissues, while the expression of EGF in tumor tissues was lower." (PMID 36959648, 2023). "This miR-21 regulates the expression of multiple tumor suppression-related genes, such as RECK, which regulates MMP9." (PMID 37834295, 2023). "The gene MMP9 was used as a positive control and is a well-known biomarker for HNSC, which showed strong protein expression only in tumor regions." (PMID 37685875, 2023). "Since the majority of produced VEGF is sequestered in the ECM deposited by tumor and stromal cells, the proteolytic release of angiogenic factors from tissue matrix, mainly mediated by MMP-2 and MMP-9, is essential for in vivo induced angiogenesis." (PMID 36759828, 2023). "MMP-9 and MMP-13 are important for the degradation of the basal layer membrane and the extracellular matrix, thus favoring tumor infiltration and metastases." (PMID 36831458, 2023).
tumor (continued). "This inhibitory effect of TEPA on TGF-β is also evidenced by a significant decrease in VIM, MMP-9 and MMP-14, which play a key role in promoting tumor invasion." (PMID 37480151, 2023). "In our experiments, direct 3D co-culture of BMSCs with tumor cells from the head and neck region (HNSCC) results in strong expression and secretion of MMP-9." (PMID 36674806, 2023). "While exploring the effects of tumor metastasis biomarkers, inflammatory factors, and cellular immunity on NETs, we found that VEGF-α, MMP-3, and MMP-9 were positively correlated with NETs, which is mechanistically plausible based on previous studies." (PMID 36910600, 2023). "qRT-PCR analysis with PANC-1 and BxPC-3 cells confirmed that circEIF3I KD inhibited the mRNA expression of MMP2, MMP9 and MMP14, which are closely related to tumour invasion and metastasis." (PMID 37689715, 2023). "We established a relationship between low MMP-9 content in sEVs and improved survival, and discovered that MMP-9 levels considerably differed between tumour types and stages, showing a positive correlation with aggressiveness." (PMID 36765669, 2023). "MMP-9 and MMP-14 were found in the cytoplasm of cancer cells and were significantly enhanced in metastatic lymph nodes compared to the primary tumour." (PMID 38203696, 2023). "Inhibition of miR-191 increase PLCD1, and then decrease β-catenin, MMP-9, C-myc, N-cadherin, CDK4 and PCNA, ultimately leading to the decrease of proliferation, migration and invasion of OSCC cells, thus exerting anti-tumor effects." (PMID 37460940, 2023). "Interestingly, another study on mouse lung cancer showed that, similar to SiglecFhigh neutrophils, neutrophils with Glut1 high expression could live longer in the tumor microenvironment, and could promote the high expression of SiglecF and MMP9, facilitating tumor progression." (PMID 37492784, 2023). "In subsequent studies, we also found that the exosomes of M2 macrophages enhanced the migration ability of tumor cells and promoted the TMT process by regulating the expression of MMP-2, MMP-9, Vimentin, and E-cadherin." (PMID 37367063, 2023). "On the contrary, the authors suggested the overexpression and demethylation of LAMA2 to suppress tumor cell invasion via the PTEN-PI3K/AKT signaling pathway and MMP-9 inhibition." (PMID 37958702, 2023). "Third, novel strategies inhibit the expressions of MMP-9 and MMP-2 and thus reduce HCC invasion, which can result in lower TNM stage in patients and lower tumor metastasis recurrence rate." (PMID 36918768, 2023). "These monocytes and macrophages in luminal tumor hubs upregulate inflammation (MMP12 and MMP9), myeloid cell recruitment (CCL2 and CCL7), and tumor growth–promoting genes (VEGF and EREG)." (PMID 37492581, 2023). "It acts as a tumour suppressor in both types of cancer, as it can suppress the secretion of MMP-2 and MMP-9." (PMID 36982551, 2023). "There is a statistically significant correlation between the expression of MMP-9 and VEGF-C, the simultaneous levels of which have significant effects on lymph node metastasis, TNM stage, and degree of tumor infiltration." (PMID 37175113, 2023). "The results of the analysis showed the presence of correlations between the expression of MMP2, MMP9 and, interestingly, TIMP1 in tumor tissue or blood." (PMID 37509417, 2023). "Strong positive correlations were found between CD31 levels in primary tumor tissue and FABP4+MMP9+MMP2+TIMP1- (r = 0.82, p < 0.05) and FABP4+MMP9+MMP2-TIMP1- (r = 0.67, p < 0.05) populations of plasma sEVs." (PMID 37109070, 2023). "Studies have indicated that SPOCK1 can promote the abnormal activation of MMP-3, MMP-9, and MMP-2, leading to directed migration of tumor cells from the edge of the tumor mass and ultimately inducing ECM remodeling." (PMID 38087364, 2023).
tumor (continued). "The publication focuses on the problem of changes in the gene expression of MMP2, MMP9 and tissue inhibitor of metalloproteinases (TIMP1) in the blood of NSCLC patients during therapy (one year after surgical resection of the tumor)." (PMID 37509417, 2023). "Nevertheless, we provide evidence that LCN2/LOXL2, LCN2/MMP9, LOXL2/MMP9, and LLM affect tumour growth and progression in a synergistic manner." (PMID 37753805, 2023). "Specific factors produced by activated T cells, tumor, and tumor stromal cells, such as VEGF, CSF, IL-6, IL-10, MMP-9, TGF-β, NF-kB, and other immune-suppressive mediators, can stimulate the proliferation and activation of MDSCs." (PMID 37857728, 2023). "The expressions of MMP-9, VEGF, Bcl-2, and Cyclin D1, involved in tumor progression, were found to increase in the radiation-alone group, but they decreased in the Rh2-alone and combination groups." (PMID 37764996, 2023). "Exposure of HCT116 tumor cells for 24 h to 64CuCl2 induced the upregulation of some hypoxia-responsive genes such as the HMOX1, MMP9, and VEGFA, the most striking overexpression being registered in the case of the HMOX1 gene." (PMID 37415761, 2023). "Compared with the CTX group, the expression levels of MMP-9, MMP-2, VEGF, bFGF, Bax, and Bcl-2 in tumor tissues were reversed by 47%, 72%, 49%, 60%, 57%, and 48%, respectively, after high-dose GFG combined with CTX treatment." (PMID 37049720, 2023). "We further distinguished between tumour cells and non‐malignant epithelial cells using several marker genes, including MMP7, MMP9, MMP13 and HOXB2." (PMID 36588094, 2023). "The results of the study revealed that PTC tissues exhibited significantly higher expression levels of MMP-2, MMP-9, and MMP-14 compared to adjacent non-tumor tissues." (PMID 38089632, 2023). "Another study found that ITGαV accelerates MMP9 activation via the TGF-β pathway, promoting tumor cell migration and proliferation, although its relationship to EAC remains to be confirmed." (PMID 37359527, 2023). "Compared with the Mod group, the expression levels of MMP-9, MMP-2, VEGF, bFGF, Bax, and Bcl-2 in tumor tissues were reversed by 67%, 74%, 50%, 63%, 80%, and 51%, respectively, after GFG combined with CTX treatment (p < 0.05)." (PMID 37049720, 2023). "The effect of several biological agents on MMP-9 activity and expression by either positively or negatively influencing PKC overall activity has been tested in different tumor models." (PMID 37958702, 2023). "Matrix metalloproteinase‐9 (MMP9) can act on the degradation of ECM and vascular remodeling, thus promoting tumor invasion." (PMID 36560848, 2023). "Through two independent validation cohorts, we finally identified five fecal tumor immune-related proteins (CAT, LTF, MMP9, RBP4, and SERPINA3) as well as a biomarker panel that had definite diagnostic value for CRC." (PMID 37313408, 2023). "In mouse skin tumors, luteolin inhibited tumor growth, decreased tumor volume and weight, and suppressed the expression of MMP-2 and MMP-9." (PMID 38248322, 2023). "Results showed that the protein levels of N-cadherin, Vimentin, Slug, p-HER2, p-EGFR, p-ERK1/2, MMP9 and MMP14 increased significantly in PLC/PRF-5LL−37 xenograft tumor; while significantly decreased in PLC/PRF-5LL−37 xenograft receiving si-LL-37 treatment." (PMID 36656313, 2023). "On the other hand, CX3CL1/CX3CR1 chemokine axis elicited adhesion and migration of TAMs, they increased the expression of matrix metalloproteinase (MMP) 2, MMP9, and MMP14 enzymes that degrade ECM, and they are concerned in tumor invasiveness." (PMID 37190507, 2023). "(D) Heatmaps showing expression of ICAM1 and ICAM-1 cleavage related proteases MMP9, ELANE, CTSG, ADAM10, and ADAM17 in normal or tumor tissue of 22 different cancer types." (PMID 37732732, 2023). "CAF-derived TGF-β upregulates matrix metalloproteinase 9 (MMP-9), which remodels ECM components and creates a favorable environment for tumor progression and metastasis." (PMID 37173977, 2023).